INS (insulin)
Diseases named in the same sentence as INS in open-access papers (continued):
Sharing a sentence is not in itself a finding about the gene and the disease.
diabetes (continued). "Diagnosis of diabetes in new patients and issues related to interrupted insulin delivery in pre-existing patients using insulin pump therapy were the most common factors associated with DKA." (PMID 25889476, 2015). "Regression analysis outcome of diabetes in Fenugreek group was positively associated with serum insulin (p < 0.01) and negatively associated with HOMA IR (p < 0.001)." (PMID 26436069, 2015). "It is well documented that STZ-induced diabetes causes a significant decrease in mean BT, and that exogenous insulin treatment is able to restore it." (PMID 25960780, 2015). "Diabetes is a chronic metabolic disease characterized by hyperglycemia, which results from an absolute or relative deficiency of insulin secretion." (PMID 25809611, 2015). "GC variants were also related to quantitative traits connected with diabetes mellitus, including plasma glucose, insulin concentrations, and insulin resistance, an association which we did not observe in our study." (PMID 26448018, 2015). "STZ is widely used in experimental animals to induce diabetes due to its toxic effect on the β-cells of pancreatic islets, resulting in a loss of insulin secretion." (PMID 26577219, 2015). "In preclinical stage of type 1 diabetes, proinflammatory cytokines generate a destructive environment for β-cells known as insulitis, which results in loss of β-cell mass and impaired insulin secretion, leading to diabetes." (PMID 26257781, 2015). "Type 2 DM is the most common form of diabetes and is usually caused by life-style factors and also related to insufficient insulin production and resistance of target tissues to insulin." (PMID 24723945, 2014). "Free IGF-I concentrations are associated with incident diabetes in women with insulin levels above, and IGFBP-1 levels below, the median." (PMID 26237614, 2014). "Even after adjusting for several known risk factors of diabetes and insulin level, the association between the baseline TyG index and the risk of incident diabetes was statistically significant, indicating that the TyG index is an independent risk factor." (PMID 24587359, 2014). "Pancreatic beta-cell death is known to be the cause of deficient insulin production in diabetes mellitus." (PMID 24803987, 2014). "Convincing evidence also comes from experimental models of insulin-deficient diabetes, where the frequency of diabetes was consistently higher in the male than female animals." (PMID 25347846, 2014). "The insulin gene mutation c.137G>A (R46Q), which changes an arginine at the B22 position of the mature hormone to glutamine, causes the monogenic diabetes variant maturity-onset diabetes of the young (MODY)." (PMID 25423173, 2014). "In a nested case-control study performed on US military service members, participants with a low serum 25(OH)D level exhibited a substantially higher risk of developing insulin-requiring diabetes mellitus than those with a higher level." (PMID 25514561, 2014). "The rate of diabetic compliance with self-management, including insulin therapy thus varies highly by country, potentially as a result of variant patient opinions and attitudes towards their diabetes care." (PMID 24802805, 2014). "In fact, diabetes has been associated with declining cognitive performance in aging, and elevated levels of circulating glucose and insulin, as found in OAL SD rats, are prevented by LTCR." (PMID 24847259, 2014). "Obesity, especially an increased visceral fat distribution, is linked to insulin resistance and the development of diabetes." (PMID 24504072, 2014). "Deficient insulin secretion, giving rise to chronically elevated blood glucose levels, is a hallmark of diabetes mellitus." (PMID 25375650, 2014). "We suspect the severely ill non-diabetic patients were more likely to be selected for blood glucose management with eProtocol-insulin, and therefore diabetes (in less severely ill patients) was associated with reduced mortality." (PMID 24886864, 2014).
diabetes (continued). "The result of either insulin deficiency or sugar level irregulated insulin secretion is diabetes mellitus." (PMID 24594290, 2014). "Research observations are increasingly making us believe that multiple events of diabetes including mitochondrial dysfunction, metabolic inflammation and altered insulin signalling cause neuronal degeneration in diabetic subjects." (PMID 25469508, 2014). "Incretin mimetic-type drugs have been implicated in GPCR-mediated regulation of insulin secretion in diabetes." (PMID 25309513, 2014). "Diabetes-related dyslipidemia always leads to excessive lipid accumulation in the kidney, which causes severe renal damage through enhancement of insulin resistance, inflammation and oxidative stress." (PMID 24651118, 2014). "Endocrine dysfunction and overt diabetes are late, inconsistent complications manifesting in roughly half of human cases, reflecting decreased insulin release with loss of islet cell mass in extensive disease." (PMID 24586530, 2014). "With regard to the markers of diabetes risk, Mexican-Americans and blacks had comparable levels of fasting insulin, but Mexican-Americans had higher levels of FBG." (PMID 24499162, 2014). "Low metabolic rate and decreased muscle-fat ratio tend to decrease insulin-responsiveness of the target tissues, which is considered as the underlying defect in this type of diabetes." (PMID 24896641, 2014). "The difference in hypoglycemia with respect to diabetes therapy is to be expected, given that insulin and insulin secretagogues are the most common cause of hypoglycemia in patients with type 2 diabetes." (PMID 25433668, 2014). "PERK (EIF2AK3) loss of function mutations in humans and mice exhibit permanent neonatal diabetes that is characterized by insufficient β-cell mass and reduced proinsulin trafficking and insulin secretion." (PMID 24915520, 2014). "Type 1 diabetes mellitus is a chronic, multifactorial autoimmune disease that involves the progressive destruction of pancreatic β-cells, ultimately resulting in the loss of insulin production and secretion." (PMID 25077824, 2014). "Univariate associations with diabetes progression measured as risk of early insulin prescription redemption in the intensive treatment group and the conventional treatment group." (PMID 25157406, 2014). "Children with African origin had less insulin anomalies than those from European countries, corroborating epidemiological data showing a low risk of diabetes in African subjects, contrary to African-American." (PMID 25220473, 2014). "Ceramide has been implicated to be involved in the pathogenesis of diabetes by mediating beta-cell apoptosis, insulin resistance and insulin synthesis." (PMID 25228885, 2014). "Our results indicated that compared with non-insulin use, there was a 23% increased risk of lung cancer in patients with diabetes." (PMID 24924771, 2014). "The Akita mutation (C96Y) in the insulin gene results in early onset diabetes in both humans and mice." (PMID 25011481, 2014). "Those genes were all previously related to the insulin pathway or diabetes, where XCR1 (encoding a chemokine receptor) even linked obesity to insulin resistance before." (PMID 25071839, 2014). "Adjusted multivariate Cox proportional hazards model for diabetes progression measured as risk of early insulin prescription redemption in the intensive treatment group and the conventional treatment group." (PMID 25157406, 2014). "The disappearance of Ucn3 from β cells that still express high levels of insulin suggests that the loss Ucn3 is an early marker of β cell stress in diabetes, occurring before the reduction in insulin expression." (PMID 25233132, 2014). "Type 2 diabetes mellitus (T2D) is characterized by insulin resistance secondary to abnormalities triggered by nutrional overload associated with deficient insulin secretion." (PMID 25177371, 2014).
diabetes (continued). "Impairments in the insulin signaling pathway in the periphery and brain have been implicated in Alzheimer's disease, diabetes, and aging." (PMID 25197672, 2014). "Specifically, both ESP and ENPP1 mutations and over expression are associated with abnormalities in glucose metabolism, insulin sensitivity, obesity and diabetes." (PMID 24839967, 2014). "In this non-experimental study, after extensive adjustment for severity of diabetes and mortality risk factors, diabetic patients treated with insulin were at increased risk for 14-year all-cause mortality." (PMID 24752580, 2014). "Although there is no clear consensus on the mechanisms that cause remission of diabetes, one common aspect among the varied bariatric surgeries is the improvement in insulin sensitivity." (PMID 25539584, 2014). "In the present study, BIX (10 and 100 mg/kg) prevented the increase in AOPP levels caused by the diabetes and this protective effect was similar to that of the antihyperglycemic drugs metformin and insulin." (PMID 24624139, 2014). "Previous research has established that changes in the expression of SOCS3, leptin, and the activation of STAT3, and AMPK are linked to the regulation of insulin signaling in obesity and diabetes." (PMID 24997069, 2014). "Considering increased prevalence of diabetes and the necessity of insulin therapy to reduce the risk of diabetes chronic complications it seems there is additional needs to insulin in Iran." (PMID 24593991, 2014). "Even after further adjustment for fasting serum insulin level, which reflects the degree of insulin resistance (model 3), the risk of incident diabetes was more than fourfold higher in the Q4 vs. the Q1 group (RR, 4.095; 95% CI, 2.701–6.207)." (PMID 24587359, 2014). "Type 1 diabetes mellitus (T1DM), also known as insulin-dependent diabetes mellitus, is an autoimmune disease that causes a progressive destruction of the insulin-producing pancreatic β cells." (PMID 26556410, 2014). "Diabetes mellitus (DM) is characterized by chronic hyperglycaemia caused by defects in insulin secretion, insulin action, or both, resulting in impaired function in carbohydrate, lipid, and protein metabolism." (PMID 24822178, 2014). "At univariate regression analysis, diabetes, BMI, waist circumference, fasting blood glucose, and insulin levels were the factors significantly associated with hsCRP concentrations in the whole study population." (PMID 25258627, 2014). "According to American Diabetes Association, diabetes mellitus (DM) is a group of metabolic diseases characterized by hyperglycemia resulting from defects in insulin secretion, insulin action, or both." (PMID 24822178, 2014). "Early in the course of diabetes and metabolic syndrome intracellular hyperglycemia due to insulin resistance causes changes in blood flow and increased vascular permeability." (PMID 24571954, 2014). "Several epidemiological studies have demonstrated that PPARG Pro12Ala is associated with insulin sensitivity and diabetes mellitus." (PMID 24447396, 2014). "It is known that certain mtDNA abnormalities are strongly associated with diabetes, particularly the A3243G mutation, which has been shown to result in impaired insulin secretion." (PMID 25532126, 2014). "Our main objective was to examine the association between 18 year weight trajectories and diabetes- and insulin-related outcomes." (PMID 24891020, 2014). "Increasing duration of diabetes was positively associated with insulin treatment (p<0.0001) and negatively associated with amylin concentration (p<0.0002)." (PMID 25750761, 2014). "Adiponectin, an adipose-specific protein, is generally negatively associated with adiposity, insulin sensitivity, and diabetes." (PMID 24575123, 2014). "Impaired insulin secretion due to either beta-cell dysfunction and/or beta-cell loss is now recognized in the pathogenesis and progression of diabetes." (PMID 25347846, 2014).
diabetes (continued). "Diabetes mellitus affects 8% of the US population and is sub-classified into type 1 (insulin-deficient) and type 2 (insulin-resistant) diabetes." (PMID 24764191, 2014). "They found that insulin therapy, depressive symptoms, and family history of diabetes were associated with lower quality of life, especially in younger patients." (PMID 25138117, 2014). "Impaired insulin sensitivity measured by euglycemic clamps predicts future risk of type 2 diabetes mellitus." (PMID 24823464, 2014). "All forms of diabetes are characterized by absolute or relative deficiencies in insulin secretion and/or insulin action associated with chronic hyperglycemia and disturbances of carbohydrate, lipid and protein metabolism." (PMID 24918095, 2014). "SFRP4 causes reduction in insulin secretion and it is over- expressed in type 2 diabetes mellitus so the inhibition of SFRP4 results in the proper secretion of insulin leading to control of diabetes type 2." (PMID 25019556, 2014). "Insulin resistance, the diminished response of target tissues to insulin, is associated with the metabolic syndrome and a predisposition towards diabetes in a growing proportion of the worldwide population." (PMID 25259572, 2014). "It is, thus, likely that obesity acts in concert with the intrinsic and apparently distinctive defects in insulin action of women with PCOS to enhance the risk of diabetes." (PMID 24705280, 2014). "Aged people are facing problems of diabetes and heart disease, whereas research suggests that antiretroviral drugs contribute to high cholesterol levels and hamper insulin production, thus increasing the risk of health problems." (PMID 25287717, 2014). "Our results show that NDM mutations gives rise to a disproportionate suppression in [Ca2+]i and insulin release, thereby causing diabetes due to the critical behavior that emerges from coupling and network dynamics." (PMID 25188228, 2014). "Diabetes results from the insufficient generation of insulin by the pancreas, or deficient insulin processing in the body." (PMID 24940623, 2014). "Physical activity is particularly important for people with diabetes, because being physically active can improve the body's ability to use insulin and facilitate weight loss." (PMID 24393171, 2014). "Here we have shown that chronic treatment with an MVT preparation improved well established diagnostic markers of diabetes such as fasting blood glucose, HbA1c, glucose tolerance, and serum insulin levels in male diabetic rats." (PMID 25160946, 2014). "There was also a better response in those with lesser obesity, perhaps a reflection that these subjects are relatively more insulin deficient than insulin resistant in the pathogenesis of their diabetes." (PMID 25180036, 2014). "Diabetes mellitus type 2, a condition often associated with chronic endogenous insulin excess, is a well-established risk factor for certain types of cancer, including endometrial tumors." (PMID 24904527, 2014). "Both those with insulin-treated diabetes and those taking oral medication have a greater risk of falls than those without diabetes." (PMID 24917889, 2014). "SNPs in the human SORCS1 gene were found to be associated with fasting insulin levels in the Mexican American Coronary Artery Diseases cohort, and with diabetes risk in women of the San Antonio Family Diabetes Study." (PMID 24752583, 2014). "In diabetes mellitus, due to insulin deficiency or resistance and the insensitivity of the cells to insulin activity, glucose transport into the cell is reduced, and this starves the cells of glucose." (PMID 24944826, 2014). "The hallmark of diabetes is hyperglycemia caused by a defect in insulin secretion and/or insulin action." (PMID 25421245, 2014). "The identification of the amplifying effect of incretins in insulin secretion has paved the way for recently developed incretin-based diabetes therapies that carry less risk for hypoglycemia (Ahrén, 2009; Drucker and Nauck, 2006)." (PMID 25373904, 2014).
diabetes (continued). "A hallmark of diabetes is reduced β-cell function measured as reduction of glucose stimulated insulin secretion (GSIS)." (PMID 24594974, 2014). "It is commonly observed in conditions associated with reduced insulin sensitivity such as obesity, lipodystrophy, and acromegaly and it is a criterion for identifying children at risk of type 2 diabetes mellitus." (PMID 25505998, 2014). "According to data from the Tromsø Eye Study, a study including 514 participants with diabetes aged from 46 to 87 years, showed that DR risk was associated with insulin use (OR 2.14, 95% CI 1.19-3.85)." (PMID 24972631, 2014). "The hyperglycemia, decreased insulin production/insulin sensitivity along with some lifestyle related problems including poor dietary habits, and hypertensions are major causes of diabetes mellitus and its complications." (PMID 24939518, 2014). "Diabetes characterized by reduced insulin sensitivity is associated with thrombosis, myocardial infarction, and cerebrovascular disease, which can lead to infarctions and white matter ischemia." (PMID 24860814, 2014). "As a conclusion, childhood adversities are associated with combined tablet and insulin-managed diabetes." (PMID 24868461, 2014). "Patients who suffer from type 2 diabetes mellitus (DM) are at increased risk of developing AD and AD patients show decreased insulin-IGF-1R signalling." (PMID 25025689, 2014). "Four studies investigating the association of glargine insulin treatment with cancers, which were published in the journal Diabetologia in 2009, created concern for both physicians and patients with diabetes." (PMID 25329887, 2014). "Type 1 diabetes mellitus is characterized by the autoimmune destruction of the pancreatic insulin-producing β-cells and subsequently absolute deficiency of insulin to maintain glucose homeostasis." (PMID 24829922, 2014). "Leklem and Hollenbeck reported that hyperglycemia induced vitamin B6 deficiency while others suggested that vitamin B6 deficiency induced a decrease in circulating insulin levels which resulted in diabetes." (PMID 25431786, 2014). "Although aerobic exercise has been traditionally prescribed for patients with diabetes, resistance training also has benefits, augmenting both strength and insulin-sensitive muscle mass and decreasing cardiovascular risk." (PMID 24699193, 2014). "Impaired insulin secretion and insulin sensitivity are the main pathogenic defects in type 2 diabetes mellitus (T2DM), and can lead to either fasting or postprandial hyperglycemia." (PMID 24932223, 2014). "Diabetes mellitus (DM) is a heterogeneous group of disorders characterized by hyperglycemia, resulting from absolutely insulin deficiency, insulin resistant and/or abnormal secretion." (PMID 24955299, 2014). "A few studies have demonstrated that VDR polymorphisms were related to obesity, diabetes, insulin sensitivity and insulin secretion." (PMID 25106919, 2014). "In short, Mn is also required for normal insulin synthesis, its secretion, and an alteration in its metabolism has been implicated in diabetes development." (PMID 24401367, 2014). "As its name suggests, IDE was originally described as an enzyme implicated in insulin metabolism and therefore of potential significance in diabetes mellitus providing one of a number of links between diabetes and AD." (PMID 25278875, 2014). "Patients with higher FVF showed higher resistance to insulin, thus obtained a higher risk of developing type 2 diabetes mellitus." (PMID 25343445, 2014). "The majority of diabetes (~90%) is type 2 diabetes (T2D) caused by a combination of impaired insulin secretion from pancreatic beta cells and insulin resistance of the peripheral target tissues, especially muscle and liver." (PMID 24397983, 2014).